JAK2 (Janus kinase 2)
Diseases named in the same sentence as JAK2 in open-access papers (continued):
Sharing a sentence is not in itself a finding about the gene and the disease.
tumor (continued). "Therefore, the JAK2 mutation status and tumor type were subjected to multivariable Cox regression analyses of PFS." (PMID 38200372, 2024). "In the future, as an increasing number of ICI treatment datasets are published, corresponding studies on whether the JAK2 p.V617F mutation can be used as a tumor antigen for immunotherapy and will also need to be conducted." (PMID 38200372, 2024). "Importantly, gp130, a common signaling receptor subunit of the IL-6 family (also known as IL-6Rβ), was moderately associated with the expression of JAK2 in normal tissue, whereas it was strongly correlated with JAK2 in tumor tissues." (PMID 38881895, 2024). "In addition to stromal STAT3, high JAK1 and JAK2 expression within the tumour cell cytoplasm was associated with reduced CSS in TNBC cases." (PMID 37199043, 2023). "TME deconvolution and cell interaction analyses allow us to identify the chemokine CCL18 secreted by tumor associated macrophages could promote tumor cell proliferation via JAK2/STAT3 signaling pathway and lead to poor prognosis of ESCC." (PMID 36850011, 2023). "Interestingly, STAT3 overexpression has been associated with poor prognosis of OS and the inhibition of JAK2/SATA3 by an inhibitor has shown promising result in OS tumor reduction in nude mice." (PMID 37491298, 2023). "In addition, artesunate, another ART derivative, enables tumor-associated monocytes to repolarize tumoricidal inflammatory monocytes against leukemic cells by inhibition of JAK2/STAT3 pathway." (PMID 35785030, 2022). "The tumor develops escape mutations: Mutations in JAK1/JAK2 may result in tumor escaping the antiproliferative effect of INF-γ." (PMID 35198442, 2022). "The JAK2/TYK2−STAT-3 signaling is known to associate with tumor promotion." (PMID 35053345, 2022). "Likewise, docetaxel‐induced senescence can reduce the size of Pten‐deficient tumours by triggering immunosurveillance when combined with Janus Kinase 2 (JAK2) inhibitor NVP‐BSK805." (PMID 35674055, 2022). "JAK1 and JAK2 mutations have also been implicated in affecting the tumour immune microenvironment." (PMID 35228677, 2022). "In tumor tissues, the expression of JAK2 is relatively higher in low‐risk patients, which may be caused by chemotherapy and resistance." (PMID 34825509, 2021). "Molecular aberrations involving various driver mutations including ALK, ROS1, KRAS, IDH1/2 and JAK2 may impact thrombotic risk in various tumor types." (PMID 32707653, 2020). "It has been confirmed that the α7 nicotinic acetylcholine receptor of tumor-associated macrophages could inhibit the metastasis of COAD through the JAK2/STAT3 signaling pathway." (PMID 32850813, 2020). "Furthermore, JAK1/JAK2-deficient tumor cell populations can silence HLA class I antigen presentation, which hinders T-cell recognition." (PMID 32111080, 2020). "No mutations were observed in the gene encoding beta-2-microglobulin (B2M), the required subunit necessary for surface expression of the MHC class I molecule, or the gene encoding interferon-receptor-associated Janus kinase 2 (JAK2) in either of the tumor specimens." (PMID 31703593, 2019). "Copy number and gene expression analyses uncovered additional potential drug targets, such as amplified and overexpressed JAK2, which has been implicated in the regulation of PD-L1 expression and appears to play a role in tumor growth and resistance to chemotherapy." (PMID 29212506, 2017). "Indeed, tumour tissue Ma-Mel-54b and the corresponding cell line harboured the JAK2 mutation already present in Ma-Mel-54a cells." (PMID 28561041, 2017).
tumor (continued). "Although low allele fractions suggest that the JAK2 p.V617F mutation is from subclonal tumor cells in the tested samples, there is an alternative interpretation pertaining to an aging-related phenomenon referred to as clonal hematopoiesis of indeterminate potential (CHIP)." (PMID 29082853, 2017). "We hypothesize that JAK2 activating mutations such as p.V617F could be associated with increased PD-L1 expression and therefore sensitize the tumor to anti-PD1 immunotherapy." (PMID 29082853, 2017). "Few other genes such as MAP3K13 and JAK2 was found to be mutated only in certain tumor pieces." (PMID 29187174, 2017). "It has been suggested that the interferon-γ-induced activation of JAK1 and JAK2 signaling pathway could suppress the tumor cell susceptibility to NK cells through up-regulation of PD-L1 expression." (PMID 27736796, 2016). "However, despite similar degrees of fatty degeneration and ROS production in GHtgSTAT5Δhep and GHtgJAK2Δhep livers, hepatic JAK2 deficiency delayed tumour formation in the GHtg background." (PMID 27713471, 2016). "Similarly, in the study of JAK2-positive myeloproliferative neoplasms, the authors compared exome-wide point mutations of 58 cells and postulated that the tumor evolved from a ‘monoclonal origin’ representing a monoclonal population of tumor cells." (PMID 25222669, 2014). "Currently, there are two pathways believed to promote tumor formation: the exogenous pathway, in which inflammation increases the risk of tumor formation, and the endogenous pathway, in which driver gene mutations such as JAK2, MPL, and CALR lead to the formation of an inflammatory microenvironment." (PMID 38348158, 2024). "Indeed, mutated ECs in PMF may represent a “neoplastic” vascular niche, which allow blood cells adhesion, vascular complications and the tumor cell growth, as demonstrated for JAK2 -mutated ECs using in vitro and in vivo assays." (PMID 34685741, 2021). "On the other hand, the mutational landscape of the tumor can also influence PD-L1 expression, which may also be overexpressed as a consequence of amplification of the chromosomal region 9p24.1 (containing PD-L1, PD-L2, and JAK2)." (PMID 33322522, 2020). "Furthermore, in melanoma, LOF mutations in JAK1 and JAK2 have been linked to the loss of PD-L1 expression in the TME resulting from dampened tumor-inherent IFN signaling, which might contribute to poor patient response to checkpoint inhibitors." (PMID 31842362, 2019). "Thus, JAK2 deficiency protected Ma-Mel-54a cells not only from anti-tumour IFNγ activity but also conserved their HLA class I-low phenotype that in turn might have hampered effective T-cell recognition of the tumour cells." (PMID 28561041, 2017). "Further examination of mutation allele fractions indicates the JAK2 p.V617F mutation has very different allele fractions than the co-occurring oncogenic mutations, suggesting they are derived from different subclonal cell populations in the same tumor specimen." (PMID 29082853, 2017). "JAK2 (tyrosine kinase 2) promotes tumor growth and treatment response in OS by regulating cell proliferation and immune response." (PMID 41158757, 2026). "In our patient, ruxolitinib produced virtually no clinical or hematologic benefit, consistent with the marked heterogeneity in JAK-inhibitor sensitivity reported in PCM1::JAK2-rearranged neoplasms." (PMID 41530508, 2026). "Although JAK2 inhibitors have demonstrated promising results, challenges such as drug resistance, the complex tumor microenvironment, and the need for pediatric-specific formulations remain." (PMID 40486651, 2025). "For example, Tumor-Associated Macrophages (TAMs) can secrete IL-6, which induces EMT in primary tumor cells through JAK2/STAT3 signaling, yielding anoikis-resistant CTCs." (PMID 41239272, 2025). "In vitro, STA has been found to impede tumor cell migration, invasion, and angiogenesis by preventing TAMs from polarizing to the M2 phenotype via the JAK2/STAT3 signaling pathway." (PMID 39974738, 2025).
tumor (continued). "Reduction in IL-6 levels translated into decreased tumour activity, indicating the central role of the IL-6/Janus kinase 2 (JAK2)/STAT3 pathway in the mechanism of action of BBR." (PMID 41226384, 2025). "Conversely, restoring SOCS2 expression or inhibiting JAK2/STAT5 signaling can suppress tumor metastasis in HB." (PMID 41393242, 2025). "Leptin stimulates tumor proliferation and epithelial–mesenchymal transition via JAK2/STAT3 signaling." (PMID 41164182, 2025). "To further investigate the synergistic effect of JAK2 pathway inhibition on the anti-tumor activity of CD19 CAR-T cells, we measured cytokine levels following co-culture." (PMID 39891728, 2025). "This study investigates the role of Prkci in regulating tumor angiogenesis through the Jak2/Stat3 signaling pathway." (PMID 40840329, 2025). "The mRNA expression levels of JAK2 in the tumor tissues of the different RRTS treatment groups were significantly reduced (P < 0.01)." (PMID 40351419, 2025). "Starting from Jak2-KO spots located in a tumor-core context, we “transplanted” the patch into another core and into a surface-like region surrounded by normal tissue." (PMID 41292874, 2025). "Inhibition with TG101209 and AZ960 reduces proliferation in tumorigenic SP/CD44+ cells, while momelotinib suppresses tumor growth by targeting JAK2 and downregulating PARP1 through the IFNGR-JAK2-STAT1-PARP1 axis." (PMID 41438763, 2025). "Western blot analysis of tumor tissues confirmed that fedratinib downregulated key signaling molecules and effector proteins, including JAK2, p-JAK2, STAT3, p-STAT3, vimentin, survivin, and cyclin D1." (PMID 41476794, 2025). "The JAK2/STAT3 pathway is an important driver of tumor progression, immune evasion, and therapy resistance; persistent STAT3 activation is linked to poor prognosis in multiple malignancies, including esophageal, breast, and colorectal cancer." (PMID 40761486, 2025). "These reprogrammed astrocytes secrete IL-6 and IL-1β, activating JAK2/STAT3 signaling in tumor cells and enabling dynamic switching between dormancy and proliferation within the CNS niche." (PMID 41562063, 2025). "proved that quercetin exhibits anti‐tumor effects in HCC LM3 cells by blocking the JAK2/STAT3 signaling pathway." (PMID 40347062, 2025). "While multiple kinases contribute to the activation of STAT3, JAK2 stands out as a critical upstream molecule that governs STAT3 activation within a variety of tumor cells." (PMID 40051568, 2025). "One study found that FTO works by inhibiting growth and glycolysis, likely by reducing the expression of APOE which acts to promote tumor growth via the IL-6/JAK2/STAT3 pathway." (PMID 40243425, 2025). "Abnormal stimulation of the JAK2/STAT3/MYC pathway promotes tumor growth, metastasis, and drug resistance." (PMID 40944417, 2025). "Preclinical studies have identified several sirtuin modulators—both inhibitors and activators—that alter tumor growth, sensitize cells to temozolomide, and regulate pathways such as JAK2/STAT3, NF-κB, and mitochondrial metabolism." (PMID 40710366, 2025). "The bond between GZMA released by cytotoxic cells and F2R on tumour cells triggers tumour suppression and T cell-mediated destruction by activating the JAK2/STAT1 pathway." (PMID 39901202, 2025). "Western blot analysis of tumor tissues showed a marked decrease in phosphorylated Jak2 and Stat3, as well as reduced Vegfa expression, in Prkci knockout tumors compared to controls." (PMID 40840329, 2025). "XH Zhou found that HCC-derived exosomes induced the overexpression of microRNA-761 (miR-761) in HCC, and reprogrammed the tumor microenvironment via targeting the SOCS2/JAK2/STAT3 pathway, which activated the tumor-associated fibroblasts (CAFs)." (PMID 41567219, 2025).
tumor (continued). "The combination of AR and JAK2/STAT1 inhibition resulted in a significant reduction in tumor growth, which was attributed to the diminished capacity for DNA damage repair and the increased propensity for apoptosis." (PMID 40001606, 2025). "Attenuation of JAK2 by miR-204 in HNSCC inhibited the JAK2/JAK3 pathway preventing tumor angiogenesis and increased sensitivity to cetuximab suggesting a tumor suppressive activity." (PMID 40176914, 2025). "STING in tumor cells aids in the tumor rejection response in prostate cancer; however, its activity is frequently inhibited in these cells, partly through the JAK2 and STAT3 pathways." (PMID 41007720, 2025). "In the development of malignant tumors, the JAK2/STAT3 signaling pathway primarily participates in the regulation of biological functions such as tumor cell growth, proliferation, migration, invasion, and apoptosis." (PMID 40936898, 2025). "In summary, these results suggest that Neo-BCV acts as a JAK2 inhibitor, exerting anti-tumor effects by inhibiting the JAK2-STAT3 signaling pathway." (PMID 39852843, 2025). "In vivo, a U2932 tumor-bearing nude mice model was employed to evaluate luteolin’s antitumor efficacy and its effects on JAK2/STAT3 pathway protein expression." (PMID 40051568, 2025). "PTEN is secreted by tumor cells via binding to TMED10 and then binds to PLXDC2 on tumor associated macrophages (TAMs) and induces inflammatory status through triggering JAK2-STAT signaling, thus contributing to the tumor suppressor function of PTEN." (PMID 40766638, 2025). "Further validation showed that overexpressed IL-11 inhibits CD8 + T cell proliferation and promotes tumor development via the Janus kinase 2/signal transducer and activator of transcription 3 (JAK2/STAT3) pathway." (PMID 40057816, 2025). "In BC, dysregulated activation of the JAK2/STAT3 signaling cascade promotes unregulated tumor proliferation, facilitates angiogenesis, enhances metastasis, and induces resistance to therapeutic agents." (PMID 41049266, 2025). "In recent years, numerous reports have indicated that JAK2 and STAT3 are closely associated with various malignant behaviors in tumor cells, including cell cycle regulation and apoptosis." (PMID 41347093, 2025). "Specifically, SIRT7 acts as a desuccinylase targeting MVP at K437, which in turn activates JAK2/STAT3 signaling to drive tumor cell proliferation, migration, and invasion." (PMID 40586636, 2025). "Others have also shown PEMF treatment to have similar effects on JAK2, leading to lower tumor-signaling inflammation." (PMID 40278322, 2025). "Meanwhile, Western blot confirmed the inhibitory effects of NCTD on p-STAT3 and p-JAK2 protein levels in tumor tissues." (PMID 40394236, 2025). "The altered expression of NOVA1 promotes tumor progression in CRC patients by modulating JAK2/STAT3 pathway." (PMID 39980011, 2025). "For KOPN-49 and REH cells, we performed a tumor rechallenge assay in which fresh tumor cells were added to CAR-T cells every three days in the presence of selective JAK2 inhibitors." (PMID 39891728, 2025). "The role of Jak2/Stat3 signaling in NB has been widely investigated, with evidence demonstrating that this pathway promotes tumor cell growth and apoptosis resistance." (PMID 40429864, 2025). "Compared to the model group, the expression levels of p-JAK2/JAK2 proteins in the tumor tissues of the Nolvadex group and all RT treatment groups were significantly lower (P < 0.01)." (PMID 40351419, 2025). "As a central transcriptional regulator, activated STAT3 contributes to chemoresistance and tumor progression through both JAK2-dependent and independent pathways, underscoring its broad relevance as a therapeutic target in gynecologic malignancies." (PMID 41463176, 2025). "Tumor-associated macrophages and fibroblasts secrete cytokines that transform normal tumor cells into CSCs via TGF-β1, STAT3/Sox2, JAK2/STAT3/snail, notch/STAT3, and IGF-II/IGF1R pathways." (PMID 39753364, 2025).
tumor (continued). "PV tumor clones arise in a relatively permissive environment, where constitutive JAK2 signaling drives glycolysis, glucose uptake, and proliferation but remains responsive to systemic metabolic modulation." (PMID 41003014, 2025). "Evidence also highlights PRLR’s role in various cancers, acting through pathways like JAK2/STAT3 to regulate tumor cell proliferation, survival, invasion, and immune evasion." (PMID 40978029, 2025). "In tumor cells, continuous stimulation of the JAK2/STAT3 signaling pathway promotes MYC expression and enhances the effects of MYC on cell proliferation and metabolism, promoting the proliferation, survival, and invasion of tumor cells." (PMID 40944417, 2025). "In NSCLC (A549 and H460) cells, UA inhibits the EGFR/JAK2/STAT3 pathway to reduce tumor angiogenesis, migration and invasion, promote apoptosis and induce cell cycle arrest at G0/G1 phase [1063]." (PMID 40490812, 2025). "In non‐kidney cells, PLA2R1 signals through the tyrosine protein kinase Janus kinase 2 (Jak2), thus controlling cell growth and senescence, protecting from tumor initiation." (PMID 40698593, 2025). "In promoting tumor proliferation and metastasis, B7-H3 primarily exerts anti-apoptotic effects via pathways such as Jak2/Stat3, PI3K/AKT, and E7/Rb, thereby enhancing tumor survival." (PMID 41463642, 2025). "This mutation intensified immune suppression by enhancing JAK2/STAT3 signaling, thereby facilitating tumor progression." (PMID 40384867, 2025). "PRLR is known to activate multiple downstream signaling pathways, among which the JAK2/STAT3 pathway plays a crucial role in tumor cell proliferation, immune evasion, and therapeutic resistance." (PMID 40978029, 2025). "For example, the upregulation of FGF signaling is found to be a critical mechanism in which the Janus kinase 2/signal transducer and activator of transcription 3 (JAK2/STAT3) pathway mediates tumor angiogenesis in NSCLC." (PMID 39796710, 2024). "In SA region, the expression of CRP (P = 0.048), gp-130 (P < 0.001), JAK2 (P = 0.004), and IL-6 (P = 0.001) was lower in tumor tissues compared with normal tissues, while the expression of IL-6R (P = 0.191) and STAT3 (P = 0.960) was comparable." (PMID 38881895, 2024). "In GBM, RORα reduced tumour-promoting inflammation by downregulation of the JAK2 (Janus Kinase 2)/STAT3 (Signal Transducer And Activator Of Transcription 3) /IL-6 (Interleukin 6) and the TNF-α/NF-κB pathway." (PMID 38378853, 2024). "Overexpression of MUC16 in lung cancer enhances tumor growth and migration, while also influencing development and metastasis through the JAK2/STAT3/GR axis, potentially contributing to chemotherapy resistance to agents like cisplatin and gemcitabine." (PMID 38361923, 2024). "At the same time, induced release of MUC16c into the cytoplasm also promotes the secretion of IL-6, which activates the JAK2/STAT3 pathway, promotes the expression of Foxp3 in tumor tissues and the abundance of tumor-associated regulatory T cells (Tregs)." (PMID 38758220, 2024). "In the present study, we demonstrated the contribution of GP73 to the amplification and transmission of GRP78-induced ERS signals for the activation of JAK2/STAT3 signals in the processing of tumor vasculature." (PMID 38939041, 2024). "Mechanistically, the alteration of CAFs-derived AKT2/CCTα axis and its-activated intratumoral JAK2/STAT3 pathway induces the resistance of FAK inhibitor in tumor treatment." (PMID 38280862, 2024). "IL-6 derived from M2 type macrophages activates the Janus kinase 2/signal transducer activator of the transcription 3 pathway, promoting angiogenesis and inflammation in tumor tissues and enhancing the invasion, proliferation, and survival of cancer cells." (PMID 38627864, 2024). "In IL-6+gp130+, IL-6+JAK2+, and IL-6+gp130+JAK2+ cells, the expression of IL-6 was lower in tumor tissues compared with normal tissues (P < 0.05), while the expression of JAK2 and gp130 was comparable (P > 0.05)." (PMID 38881895, 2024).